RNU6-535P (RNA, U6 small nuclear 535, pseudogene)
Gene: Small nuclear RNA gene on chromosome 10 (7,486,703 to 7,486,809, reverse strand). Ensembl gene ENSG00000207453.
Homologues: Orthologues: chimpanzee U6 (97% identical), macaque U6 (90% identical), rabbit U6 (78% identical). Paralogues in human: RNU6-1060P (86% identical), RNU6-949P (86% identical), RNU6-12P (85% identical), RNU6-13P (85% identical), RNU6-166P (85% identical), RNU6-25P (85% identical), RNU6-32P (85% identical), RNU6-33P (85% identical), RNU6-36P (85% identical), RNU6-41P (85% identical), RNU6-47P (85% identical), RNU6-842P (85% identical), and 1287 more.